HIF1A (hypoxia inducible factor 1 subunit alpha)
Diseases named in the same sentence as HIF1A in open-access papers (continued):
Sharing a sentence is not in itself a finding about the gene and the disease.
prostate carcinoma (continued). "Here we identified a novel regulatory mechanism that hypoxia-responsive and HIF1α-regulated miR-182 acts as a positive regulator of HIF1α signaling by targeting negative regulators PHD2 and FIH1 in prostate cancer cells." (PMID 26205124, 2015). "To validate these data, we analyzed the expression of HIF-1α in PC3 and another prostate cancer cell line-22Rv1, which are both over-expressing ERβ2." (PMID 26010887, 2015). "DFO treatment dramatically increased the HIF1α expression in DU145 and PC-3 prostate cancer cells, which is concomitant with a reduction in protein levels of PHD2 and FIH1." (PMID 26205124, 2015). "Consistently, knockdown of KLF5 in PTEN-insufficient human prostate cancer cells increased tube formation and migration in HuVECs, enhanced PI3K/AKT activity, and upregulated HIF1α, VEGF and PDGF." (PMID 25896712, 2015). "miR-182 overexpression in PC-3 prostate cancer xenografts decreased PHD2 and FIH1 expression, elevated HIF1α protein levels, and increased tumor size." (PMID 26205124, 2015). "Lastly, we revealed that the levels of both miR-182 and HIF1α were elevated, while the expression PHD2 and FIH1 was downregulated in a mouse model of prostate cancer." (PMID 26205124, 2015). "We also detected mRNA expression of HIF1α, VEGF and PDGF-B in human prostate cancer cells with altered KLF5 expression." (PMID 25896712, 2015). "We performed Western blotting to detect HIF1α expression and ELISA to detect the secretion of VEGF and PDGF-B in prostate cancer cells, whereas PDGF-D is undetectable by ELISA due to a low level of expression." (PMID 25896712, 2015). "Following treatment of prostate cancer cells with the PI3K inhibitor, wortmannin, MSeA was shown to induce a downregulation of HIF-1α and a concomitant upregulation of REDD1 protein in an apparent AKT independent manner." (PMID 24515947, 2014). "For these two prostate cancer cell lines, nobiletin has the apparent ability to suppress cell viability concentration-dependently through multiple pathways (VEGF, HIF-1α, AKT phosphorylation, cMyc, and NF-κB)." (PMID 25342300, 2014). "The expression of HIF-1α and VEGF in prostate cancer cells and xenografts was detected by Western blot analysis." (PMID 24886405, 2014). "One notable observation in the current study was that prostate cancer cells expressing NANOG and OCT4 were also positive for HIF-1α reactivity." (PMID 25120646, 2014). "In another study, the small molecule L-mimosine promoted HIF-1α expression, as well as NDRG1 expression, in prostate cancer cells, thereby inhibiting prostate cancer proliferation." (PMID 25232961, 2014). "Although these data cannot be extrapolated to prostate cancer cells but it is evident from these experiments that MSeA is changing the redox state of cells in hypoxia and thereby increasing REDD1 and decreasing HIF-1α." (PMID 24515947, 2014). "We report a nuclear physical interaction between ARRB1 and HIF1A in prostate cancer cells and show that it occurs at the chromatin level, where recruitment of ARRB1 to HREs at functional promoters of HIF1A targets upon hypoxia is HIF1A dependent." (PMID 24837709, 2014). "When specimens were diagnosed as prostate cancer, immunohistochemical analysis of the four different stem cell markers (NANOG, OCT4, CD133 and NESTIN) and hypoxia-inducible factor (HIF)-1α was performed." (PMID 25120646, 2014). "Liu and his cooperators demonstrated that inhibition of miR-21 can decrease HIF-1α and VEGF proteins expression in prostate cancer cells." (PMID 23951172, 2013). "A recent report showed that high expression of VEGF, a HIF-1α target gene, facilitates EMT through promoting Snail nuclear localization in prostate cancer." (PMID 23786654, 2013).
prostate carcinoma (continued). "In another study in prostate cancer, ER beta was reported to repress the transcription of VEGF and destabilize HIF-1α." (PMID 24348555, 2013). "Artificial over-expression of miR199b by using adenoviral vectors in prostate cancer PC-3 and DU145 cells significantly down-regulated HIF-1α, together with reduced cell growth and increased cell death." (PMID 23594994, 2013). "In DU145 cells, a prostate cancer cell line with moderate invasive potential, only TRIB2 depletion was effective in abrogating TNFα-induced HIF-1α accumulation." (PMID 22355351, 2012). "We have recently demonstrated that CAFs induce EMT of prostate cancer cells through a proinflammatory pathway involving COX-2 (cycloxygenase-2), NF-κB (nuclear factor-κB), and HIF-1α." (PMID 22272371, 2012). "Hypoxia inducible factor 1 alpha (HIF-1α) is involved in cancer angiogenesis, proliferation, erythropoiesis, and androgen resistance in prostate cancers." (PMID 23243443, 2012). "Apigenin reduced HIF-1α stability and HIF-1α mRNA expression in human prostate cancer PC3-M cells via PI3K/Akt/GSK-3β pathway." (PMID 22844340, 2012). "The prognostic significance of EGF-receptor (EGFR), HIF1α and VEGF-A in prostate cancer is somewhat disputed." (PMID 22546016, 2012). "In our study, approximately three quarters of all prostate tumors strongly expressed HIF1α, and VEGF-A, a number that is similar to the figures reported by others in prostate cancer." (PMID 22546016, 2012). "miR-210 is induced by hypoxia-inducible factor-1 alpha (HIF-1α) to promote cell survival and adaptation to hypoxic environmental conditions, and HIF-1α alters miR-101 expression in a prostate cancer model." (PMID 22505930, 2012). "Among these six, HLF, JUN, c-MYC, EGR1, SMAD1, and HIF1A, were also identified as PTEN-controlled TFs, and four, ESR2, MYB, RELA, and USF1, as prostate cancer-related TFs." (PMID 22347425, 2012). "The recent study showed that the expression of HIF-1α target gene VEGF, a growth factor that can promote EMT in prostate cancer." (PMID 21887310, 2011). "Inhibition of coexpression of HIF-1α and VEGF was observed by immunofluorescence in PC-3 and DU145 prostate cancer cells." (PMID 21819554, 2011). "HIF1α is a logical candidate to control OST expression, because it is overexpressed in prostate tumors as well as in human prostate cancer cell lines." (PMID 22135748, 2011). "For example, HIF-1α overexpression under standard growth conditions was detected by immunoblot in metastatic breast cancer MDA-MB-231 cells and DU145 prostate cancer cell lines." (PMID 19347037, 2009). "The mechanism may involve HIF1α lactylation enhancing the transcription of the KIAA1199 gene, thereby promoting angiogenesis and tumor development in prostate cancer." (PMID 40443721, 2025). "In prostate cancer cells, curcumin inhibits the activation of the ERK1/2/c-Myc/HIF-1α signaling axis and reduces the activity of rate-limiting enzymes such as HK1/2, PFKP, and PDH in a concentration-dependent manner, thereby blocking glycolytic metabolic flux and glucose consumption." (PMID 41515171, 2025). "Furthermore, in various cancer types, including lung, breast, cervical, and prostate cancers, curcumin downregulates PKM2 through the inhibition of the mTOR/HIF-1α signaling pathway, which disrupts glucose uptake and lactate release." (PMID 41515171, 2025). "Quercetin inhibited EMT and down-regulated HIF-1α levels and MMP-9 in prostate cancer cell lines." (PMID 39859345, 2025). "Functionally, both HIF1α and PHD1 promote prostate cancer cell proliferation and migration." (PMID 40643528, 2025). "Apigenin decreased hypoxia‐induced activation of HIF‐1α and Akt pathways in metastatic prostate cancer cells, by decreasing both the stability of HIF‐1α protein and down‐regulating steady state HIF‐1α mRNA in normoxic and hypoxic conditions." (PMID 40781971, 2025). "Furthermore, HIF1α also drives the EMT in hepatocellular and prostate carcinoma through Wnt/β-catenin signaling." (PMID 38361941, 2024).
prostate carcinoma (continued). "The development and progression of prostate cancer through the P4HA1 pathway involves facilitating the growth and survival of cancer cells, activating certain cellular signaling pathways, and controlling the activity of a key transcription factor HIF-1α." (PMID 38791417, 2024). "As observed in prostate cancer PC-3 and LNCaP cells, the interaction of 38 with the N-terminal ATP binding domain of HSP90 induces destabilization and degradation of numerous HSP90 client proteins by the ubiquitin–proteasome pathway, among them HIF-1α." (PMID 38667760, 2024). "Focusing on the hypoxic state of IDCP, patients with prostate cancer and IDCP may benefit from inhibitors targeting HIF1A." (PMID 38732035, 2024). "Briefly, there is a strong correlation between the expression of both HIF-1α and NOX, and this could serve as a potential chemoprevention target in controlling prostate cancer under hypoxic conditions." (PMID 36787054, 2023). "Besides, HIF-1α promotes the EMT and the following enrichment of stem-like side population cells in prostate cancer." (PMID 37143105, 2023). "Also, it is mentioned in many studies that the predicted targets HIF1A, AVRP1A, NHS, INSL4 have a very important role in the progression of prostate cancer." (PMID 36326314, 2022). "In another study, CAF has been shown to induce HIF-1α-dependent oxidative response, thereby increasing the expression of CXCR4 and interleukin-6 (IL-6) receptors in prostate cancer cells to promote epithelial-to-mesenchymal transition (EMT) and invasion of the tumor cells." (PMID 35884382, 2022). "Decreased levels of hsa-miR-494-3p, hsa-miR-3128, hsa-miR-8084 and therefore likely to increase levels of targets HIF1A, AVRP1A, NHS, INSL4 may be novel biomarker candidates for early-stage diagnosis and treatment of prostate cancer." (PMID 36326314, 2022). "Indeed, MAO-A knockdown reduces tumor growth and metastasis by inhibiting HIF-1α and EMT in aggressive prostate cancers." (PMID 36233054, 2022). "In prostate cancer samples, the co-localization of HIF-1α, OCT4 and Nanog suggest that the production of CSCs may be regulated by HIF-1α by regulating stem factors." (PMID 36014432, 2022). "A pioneer work performed in 2014 demonstrated for the first time that aggressive prostate cancers had increased MAO-A expression and that knockdown of MAO-A reduced tumor growth and metastasis in vivo through HIF-1α and epithelial-to-mesenchymal transition blockade." (PMID 36233054, 2022). "HIF-1α promotes the expression of SNAIL and Slug, thereby accelerating the progression of EMT under hypoxic conditions and enhancing the initiation of metastasis in prostate cancer." (PMID 36139386, 2022). "In prostate cancers, upregulated Snail suppressed the transcription of miR-128, a negative regulator of S6K1 mRNA, resulting in increased expression of S6K1, hypoxia-inducible factor 1 subunit alpha (HIF1α), and pyruvate kinase M 2 (PKM2)." (PMID 35879299, 2022). "It has been shown that hypoxia activates TGF-β signaling via HIF-1α to convert fibroblasts into myofibroblasts, which in turn induces C-X-C motif chemokine 13 (CXCL13) expression for B cell recruitment and metastatic progression of prostate cancer cells." (PMID 35884382, 2022). "Berberine could increase radiosensitivity of prostate cancer cells through inhibiting the expression of HIF-1α and VEGF, which indicated that it could be an adjuvant in radiotherapy of prostate cancer." (PMID 35889396, 2022). "In surgical studies of breast and prostate cancer, short-term inhibition of COX-2 has shown an increase in apoptosis in neoplastic cells and a reduction in the proliferation, angiogenesis, and expression of HIF-1α." (PMID 35252243, 2022). "Clinicopathological features of prostate cancer in relation to HKII and HIF-1α protein expression." (PMID 34220956, 2021).
prostate carcinoma (continued). "Chrysin contributed to increased HIF-1α prolyl-hydroxylation, leading to its ubiquitination and subsequent degradation, and interfered with HSP90/HIF-1α connections, thus reducing HIF-1α stability in a human prostate cancer (DU145) cell line." (PMID 33401572, 2021). "One study attempted to compare the location of [18F]-FAZA-PET with immunohistochemical staining of hypoxia markers hypoxia inducible factor-1α (HIF-1α) and carbon anhydrase XI (CAXI) to validate [18F]-FAZA-PET as a useful hypoxia identification tool in prostate cancer patients." (PMID 34073301, 2021). "In contrast to the regulation of HIF-1α on PDGF, it has also been demonstrated that PDGF-BB treatment can rapidly increase the nucleus level of HIF-1 to activate transcription of myeloid cell leukemia-1 (Mcl-1) in human prostate cancer cells." (PMID 34445528, 2021). "Moreover, zinc induced HIF-1α proteasomal degradation and suppressed VEGF expression in prostate cancer and glioblastoma." (PMID 34926261, 2021). "In line with this hypothesis, Mimeault and Batra reported that AKT stabilizes HIF-1α and, thus, promotes HIF-1α-dependent CXCR4 expression in breast and prostate cancer cells." (PMID 34064589, 2021). "Given the close correlation between PRKAR2B and HIF‐1α, we hypothesized that PRKAR2B might be induced by hypoxia in prostate cancer." (PMID 33025691, 2020). "Moreover, suppression of TRPM7 abrogated HIF-1α/Annexin A1 signaling pathway to reduce hypoxia-induced EMT, cell migration, and invasion of androgen-independent prostate cancer cells." (PMID 32215176, 2020). "SC144-induced alterations of HIF-1α and NDRG1 were also confirmed in prostate cancer cells." (PMID 32550915, 2020). "It has been demonstrated that ERRα expression is correlated with castration-resistant prostate cancer, and it could promote tumor progression by targeting a number of cancer-related genes, including VEGF-A, WNT5A and TGFβ1, and WNT11 and HIF-1α." (PMID 33014785, 2020). "TRPM7 knockdown significantly reduced HIF-1α protein level without change of HIF-1α gene transcription in androgen-independent prostate cancer cells insulted with hypoxia." (PMID 32215176, 2020). "In a study of prostate cancer patients, neither HIF-1α nor -2α correlated with Ktrans or Kep values, but there were only 15 patients in the final analysis." (PMID 31437208, 2019). "HIF1A cooperates with FOXA2, a transcription factor expressed in NE tissue, to induce several HIF1A target genes that are required for hypoxia-mediated NE phenotype and metastasis in prostate cancer." (PMID 32039001, 2019). "In prostate cancer cell lines, exogenous expression of human DDAH1 increases cell proliferation, migration and invasion, and induces expression of multiple NO-regulated genes such as VEGF, HIF-1α, and iNOS." (PMID 31993367, 2019). "We not only analysed the expression levels of CFTR in HT-29 cells, HIF-1α in HEK-293T cells, GAPDH in liver tissue of mouse, and serum AFP in HCC patients, but also the glycosylation changes in the sera of prostate cancer patients, in combination with the optimised fixation method." (PMID 31040299, 2019). "Taken together, our results proved that HIF1α could promote the proliferation and migration of PC-3 cells by direct upregulating ATG5 and autophagy level in PC-3 prostate cancer cells." (PMID 31700698, 2019). "HIF-1α levels are also increased in tumors with activated PI3K/AKT signaling; this mechanism is well understood in prostate cancer cells where the inactivation of PTEN facilitates the HIF-1-mediated gene expression, leading to increased tumor vascularity and growth compared to cells expressing PTEN." (PMID 30754624, 2019). "In prostate cancer, upregulation of p22phox was also reported to activate PI3K/Akt pathway and extracellular signal-regulated kinase 1/2 (ERK1/2) pathway and subsequently induce HIF-1α via ROS signaling." (PMID 30800222, 2019).
prostate carcinoma (continued). "Taken together, our results, for the first time, proved that HIF1α could promote the proliferation and migration of PC-3 cells by direct upregulating ATG5 and autophagy level in PC-3 prostate cancer cells." (PMID 31700698, 2019). "On the contrary, LNCaP cell line, representative of the less aggressive phenotype among prostate cancer subtypes, neither showed the constitutive presence of HIF-1α protein nor the localization of PKM2 in the nuclear compartment." (PMID 31500219, 2019). "Moreover, they found that miR-182 plays an important role in prostate cancer, which enhances HIF1α signaling by targeting PHD2 and FIH1 in prostate cancer." (PMID 30597923, 2018). "Pyrroloiminoquinone alkaloids (No. 23) from the marine sponge Latrunculia sp., which were identified as novel HIF-1α/p300 inhibitors, interrupted the protein-protein interaction between HIF-1α and p300, and potently inhibited the growth of HCT 116 and prostatic carcinoma cell lines in vitro models." (PMID 29786660, 2018). "Then we detected HIF-1α expression in prostate cancer cells under hypoxic conditions and with or without propofol and found that hypoxia induced HIF-1α upregulation, whereas propofol suppression of HIF-1α expression reversed this result." (PMID 29568752, 2018). "Besides, several miRNAs such as miR-182 and miR-101 can be included by hypoxia in prostate cancer, epigenetic modulators such as Enhancer of zeste homolog 2 (EZH2) can also be regulated by HIF-1α induction." (PMID 29699590, 2018). "In summary, our studies suggest that MSCs might promote prostate cancer growth in the inflammatory microenviroment through producing higher levels of PDGF and VEGF through the HIF-1α pathway and facilitating tumor angiogenesis." (PMID 29268703, 2017). "At present, two anti-angiogenic drugs are being tested in the phase III setting for men with prostate cancer, carbozantinib (a dual VEGFR2/MET inhibitor) and tasquinimod (down-regulator of HIF-1α), which previously showed beneficial and encouraging results on phase II trials." (PMID 28143503, 2017). "Importantly, we observed that PHF8 is highly expressed in clinical androgen deprived prostate cancer samples and expression of PHF8 correlates with increased levels of HIF1α and HIF2α." (PMID 27991916, 2016). "Takes part in a positive feedback loop to stabilize hypoxia-induced HIF-1α expression. lncRNA-p21 excludes the binding of HIF-1α to VHL (an ubiquitin E3 ligase) in prostate cancer." (PMID 27551267, 2016). "SK1 has been reported as a downstream target of HIF-1α in other systems, whereas in prostate cancer this relationship was not investigated." (PMID 27821815, 2016). "We assessed whether pristimerin suppresses hypoxia-induced HIF-1α and SPHK-1 in several prostate cancer cell lines (PC-3, DU145, and LNCaP)." (PMID 27581969, 2016). "To determine whether all these mechanisms exist in prostate cancer cells, we examined the levels of phosphorylated (p)-P70S6 Kinase (P70S6K) and HIF-1α in PC-3 and DU145 cells treated for 24 h with 5 nM docetaxel and 100 nM RAD001." (PMID 27821815, 2016). "Above results have shown that miR-182 could enhance the expression of HIF1α and VEGF in prostate cancer cells." (PMID 26205124, 2015). "We also used transient transfection of siRNAs to knock down KLF5 and adenoviral infection to transiently express KLF5 in the two prostate cancer cell lines, and confirmed that knockdown and overexpression of KLF5 respectively increased and decreased the expression of HIF1α." (PMID 25896712, 2015). "In addition, our recent results suggest that HIF-1α is important for TWIST1 expression and prostate cancer cell invasion." (PMID 26520789, 2015). "We show here that there is a strong correlation between ERβ2 expression and HIF-1α protein level but not mRNA level in the prostate cancer cell lines PC3 and 22Rv1." (PMID 26010887, 2015). "Berberine may inhibit the expression of HIF-1α and VEGF and thus confer radiosensitivity on prostatic cancer cells." (PMID 24886405, 2014).